PML (PML nuclear body scaffold)
Diseases named in the same sentence as PML in open-access papers (continued):
Sharing a sentence is not in itself a finding about the gene and the disease.
tumor (continued). "Histone lactylation can upregulate AlkB homolog 3 (ALKBH3), which in turn suppresses m1A modification of speckled protein 100A (SP100A), weakening the formation of tumor-suppressive promyelocytic leukemia (PML) protein condensates and facilitating the malignant transformation of tumor cells." (PMID 40584966, 2025). "Additionally, the green tea polyphenol epigallocatechin-3-gallate in combination with ATRA supports the degradation of the PML/RARα oncogene, restoring PML and inducing tumor promyelocyte differentiation." (PMID 40333775, 2025). "This stabilization suggests that nuclear p62 condensates may act indirectly as tumor suppressors by enhancing PML-NB integrity and function." (PMID 41247240, 2025). "However, PML::RARA disrupts PML nuclear bodies (PML-NBs), impairing the tumor-suppressive functions of PML and promoting cell survival." (PMID 41440764, 2025). "In summary, in tumor, phase separation participates in multiple physiological processes such as DNA damage repair, transcriptional regulation, signal transduction, and the formation of PML bodies and SGs." (PMID 38383403, 2024). "Notably, the complexity of PML’s activities is evident in cancer biology, where it exhibits a dual role as both a tumor suppressor and a tumor promoter, depending on the cellular context and the specific signaling pathways involved." (PMID 39388244, 2024). "PML also regulates neovascularization, tumor metabolism, and tumor stem cell maintenance." (PMID 39253293, 2024). "In this study, we showed, for the first time, that the localization of PAI-1 in PML bodies is highly correlated with the growth potential of endothelial cells and could impart a strong link to its age-related functions and tumor progression." (PMID 39161580, 2024). "The loss of function of PML and RARα is implicated in APL pathogenicity, and inactivation of the tumor suppressor activity of PML might promote cancer development by inducing genome instability." (PMID 39006762, 2024). "PML tumor suppressive functions have been known since the creation of PmlKO mice models." (PMID 38611029, 2024). "On the other hand, PML expression is reduced in many tumor types, favoring pro-tumorigenic effects of USP22 on cell cycle progression, but it remains unclear how USP22 regulates the tumor-associated functions of PML." (PMID 38467608, 2024). "Structure-function analysis of endogenous PML in tumor models in vivo could also provide invaluable mechanistic insights into therapy response." (PMID 37382966, 2023). "In agreement with this, parental or lines generated by culturing KD PML tumors expressed higher levels of HIF1a protein and its target, VEGFa that may account for a higher tumor angiogenic activity." (PMID 37518985, 2023). "More broadly, possibly through the control of cytokine signaling, PML contributes to the cross-talk between the tumor and the microenvironment and could modulate response to immune therapies, as proposed for inhibitors of sumoylation." (PMID 37382966, 2023). "We next tested the impact of PML ablation on cells grown in 3D as tumor spheres." (PMID 37518985, 2023). "Results from these experiments show that passage one (P1) KD PML from either parental or tumor‐derived lines had a lower TSF ability (20–30%) than controls, under either normoxic or hypoxic (3% oxygen) conditions, although in the latter a general increase in TSF was found." (PMID 37518985, 2023).
tumor (continued). "In these situations where PML favors tumor maintenance, it could emerge as a relevant therapeutic target." (PMID 37382966, 2023). "The PML protein is a tumor suppressor and an important organizer of PML NBs." (PMID 35408996, 2022). "The enigmatic functions of both PML and UTX suggest that their tumor suppressor activities could be linked to the disruption of oncogenic biomolecular condensates." (PMID 35406602, 2022). "PML mutants resistant to CK2 phosphorylation displayed increased tumor-suppressive functions." (PMID 36009534, 2022). "Furthermore, analysis of biopsies for potential proteomic predictive biomarkers of response showed that patients with lower levels of PML or PLOD3 in tumor had more favorable clinical outcomes." (PMID 35641481, 2022). "PML protein is known as a classic pro-apoptotic and growth-suppressive tumor suppressor." (PMID 35641481, 2022). "Patients with lower tumor PML or PLOD3 expression had favorable ORR and PFS." (PMID 35641481, 2022). "Thus, DZNeP eliminated the motile phenotypes in the PML OE condition and reduced the motility of the cells that managed to detach from the tumor core and migrate." (PMID 34208139, 2021). "Furthermore, as also shown in previous reports, PML OE reduced the tumor growth expansion of the 3D spheroids, also indicating lower proliferative capacity." (PMID 34208139, 2021). "The tumour suppressive activity of PML was later extended to various solid tumours." (PMID 34215258, 2021). "However, the specific role of PML in cancer remains to be explained, as PML can have both tumor-promoting or tumor-inhibiting effects regarding the type or the tissue origin of the tumor." (PMID 34208139, 2021). "Not surprisingly, therefore, SUMO-dependent PML NB integrity has been implicated in regulating many physiological processes including tumor suppression, metabolism, drug-resistance, development, cellular stemness, and anti-pathogen immune response." (PMID 34513832, 2021). "In addition, the overexpression of PML is associated with high invasive tumor grade in TNBC patients, suggesting PML as a putative therapeutic target in TNBC." (PMID 34503213, 2021). "Given that suppressed IP3R3-mediated Ca2+ flux and apoptosis has been linked to other major tumor suppressors PTEN, BAP1, and PML, in driving tumorigenesis, our above analyses suggest that this may also play a role in SMARCA4/2-deficient cancers." (PMID 34518526, 2021). "PML mediates tumor growth and invasion through distinct cellular mechanisms." (PMID 34208139, 2021). "PML co-localizes to PML nuclear bodies where it functions as a tumor suppressor." (PMID 34316716, 2021). "Although PML is crucial for the activities of critical tumor-suppressive pathways, the mechanism by which PML is efficiently regulated remains unknown." (PMID 32826889, 2020). "The stability of PML-NBs plays a critical role in the immune response and tumor suppression." (PMID 32782452, 2020). "PML functions in various biological pathways as a tumor suppressor and as an ALT-related gene." (PMID 32784588, 2020). "We suggest here for the first time that ALT may be coupled by HR in polyploid tumor cells with inverted meiosis (IM) in PML-APB bodies for recombination (and possibly counting) of homologous chromosomes." (PMID 32316332, 2020). "PML has been a paradigmatic tumor suppressor since its discovery." (PMID 31570853, 2020). "PML, through its transient or facultative interactions, facilitates tumor suppressive roles." (PMID 33396222, 2020).
tumor (continued). "Thus ERβ-PML network interestingly curbs oncogenesis by inhibition of anti-apoptotic molecule and stabilizing a tumor-suppressor." (PMID 31506431, 2019). "Decreased PML levels can also promote tumor growth by enhancing cellular autophagy." (PMID 30931098, 2019). "ATO can induce tumor cell differentiation, promote degradation of PML/RARα fusion protein, block specific intracellular signaling pathways, and trigger apoptosis by activating the intracellular caspase cascade, downregulating Bcl-2 expression and inhibiting NF-kB." (PMID 31632492, 2019). "A body of evidence indicated that PML is a tumor suppressor and promising therapeutic targets, might be associated with chemo-resistant as well." (PMID 31152142, 2019). "Surprisingly, this mechanism was revealed to involve promyelocytic leukemia (PML), generally known as a tumor suppressor, which deacetylates PGC-1α, leading to activation of PPAR signaling to promote FAO, thereby supporting the survival, growth, and malignant phenotype of breast cancer cells." (PMID 30771209, 2019). "IPA-derived relational networks reflect the possible roles of known oncogenes, e.g., MYC and HDGF (REF: PMID 27543492), overexpressed in B-raf V600E_high samples, and tumor suppressors, e.g., PML and toll-like receptors (PMID: 30127747, 29416846), downregulated in B-raf V600E_high samples." (PMID 31835364, 2019). "Therefore, PML is regarded as a potent tumor suppressor in in vitro (biochemistry, cell culture experiments) and in vivo (model organisms)." (PMID 29888200, 2018). "Since then, evidence has accumulated that PML functions as a tumor suppressor." (PMID 29416846, 2018). "As a tumor suppressor, PML protein abundance is frequently low in tumorous tissues." (PMID 29416846, 2018). "This and other reports have lead to the suggestion that PML may act as both a tumor suppressor and an oncogene, depending on the cellular context." (PMID 29888200, 2018). "In addition, previous studies have reported that PML functions as an important tumor suppressor, and PML regulates numerous fundamental processes, such as apoptosis, cellular proliferation and cell cycle regulation." (PMID 28333959, 2017). "Also, IP3Rs are modulated by tumor suppressors, such as PML, as part of a homeostatic program to support normal cell growth by balancing adequate apoptosis susceptibility and regulated autophagy flux." (PMID 28725634, 2017). "PML is a tumour suppressor and regulator of cell differentiation." (PMID 28317833, 2017). "Thus, KLHL20-mediated PML ubiquitination results in not only the inhibition of PML tumor-suppressive functions but also a robust induction of various tumor hypoxia responses to contribute to the aggressiveness of diseases." (PMID 27200299, 2016). "PML SUMOylation is essential for PML NB formation and apoptosis in tumor-derived cells." (PMID 27031987, 2016). "Indeed, KLHL20 confers tumor-promoting functions, such as transformation, migration, and survival, which are dependent on PML downregulation." (PMID 27042198, 2016). "Importantly, KLHL20 is demonstrated to act as a positive regulator of various tumor hypoxia responses through PML degradation." (PMID 27042198, 2016).
tumor (continued). "Furthermore, PML plays an essential role in the regulation of the tumor suppressive function of PTEN, through HAUSP." (PMID 27184141, 2016). "Furthermore, KLHL20 is expected to elicit certain oncogenic roles through blocking the tumor suppressive effects of PML." (PMID 27042198, 2016). "Thus, PML in normal and tumor stem cells has distinct functions, which are likely to be mediated by different PML downstream pathways." (PMID 26510911, 2015). "Emerging evidence suggests that cytoplasmic PML can also have tumor suppressor functions." (PMID 26539288, 2015). "Furthermore, disruption of PML by the shRNAs severely impaired tumor growth of the GSC-derived xenografts." (PMID 26510911, 2015). "One classical example is the tumor suppressor PML (promyelocytic leukemia protein)." (PMID 26284195, 2015). "Additionally, intra-tumor genomic heterogeneity was studied by fluorescence in situ hybridisation (FISH) in PML gene (15q22), exclusively altered in P1 sample regarding CGH results." (PMID 26620706, 2015). "Thus, we conclude that PKA activation is responsible for β-catenin relocalizing to PML bodies in the nuclei of tumor osteoblasts." (PMID 25299576, 2014). "These proteins do not appear to act in a common pathway or to share structural features in common, which may account for the diverse functions of PML NBs, such as DNA damage response and repair, apoptosis, tumor suppression, and transcriptional regulation." (PMID 24728382, 2014). "Considering that PML is an important tumor suppressor, we propose that nuclear portion of LC3 protein may associate with PML to control cell growth for prevention and inhibition of cancer occurrence and development." (PMID 25419843, 2014). "However, PML, which had been considered a tumor suppressor gene for over 20 years, is now found to exert oncogenic functions in specific tumor contexts precisely because of its metabolic role." (PMID 24575390, 2014). "A future challenge will be to understand what are the discriminating genetic co-factors of PML oncogenic or tumor suppressive functions and which other, if any, tumor type might benefit of PML tumor-promoting functions." (PMID 24575390, 2014). "We hope that the unexpected finding of “PML surfing into the YAP-Hpo tumor suppressor pathway” will allow us to better understand the entire Hpo signaling network, and to design systems biology approaches to fight cancers caused by the genetic lesions that map within, and affect the network." (PMID 23459691, 2013). "More detailed studies are warranted in order to categorize diverse tumor types for these opposing activities of PML, and ultimately to explore the therapeutic potential of PML-targeting compounds, alone or in combination with drugs that target PML-linked pathways." (PMID 23936764, 2013). "Hence, the simple notion that PML is a general tumor suppressor that serves as a strong pro-apoptotic and pro-senescence determinant is not supported by the available data." (PMID 23847764, 2013). "If this is the case, PML function in support of self-renewal may be more important than its tumor-suppressor activities and the applicability of well-established therapeutic agents, like As2O3, which lead to PML degradation may be much broader than expected." (PMID 23847764, 2013). "In this review, we examine how the concept of tumor-suppressor gene has evolved until now and then systematically assess whether this assumption for PML is supported by unambiguous experimental evidence." (PMID 23847764, 2013). "The promyelocytic leukemia (PML) tumor-suppressor is the key organizer of PML Nuclear Bodies (NBs)." (PMID 23847762, 2013). "Several lines of evidence indicate that PML is a potential tumor suppressor." (PMID 23761861, 2013).
tumor (continued). "Since CSCs very often constitute only a minor fraction of the whole tumor population, PML expression may have gone unnoticed in previous analyses, underestimating the importance of PML in the maintenance of a specific tumor." (PMID 23847764, 2013). "In recent years, a growing body of work has revealed that PML may provide a selective advantage for tumor cells in certain settings, thus presenting PML as a therapeutic target." (PMID 23936764, 2013). "To explore if the number of PML-NBs counted in a 4 μm tissue section is related to the size of the nucleus, we correlated the number of PML-NBs to the nuclear surface area in 20 individual tumor cells per case in 6 different cases (3 cases with low PML-NB numbers and 3 with high PML-NB numbers)." (PMID 24009715, 2013). "In addition, studies showed that PML protein accumulation is down-regulated in many cancer types suggesting that PML is a tumor suppressor." (PMID 22947142, 2012). "But this statement is also true for the other E3 ligases acting on PML, as it could restore expression of the tumor suppressor PML which is lost or reduced in many different human tumors." (PMID 23293771, 2012). "Thus, PML likely maintains the expression levels of class I HLAs as part of its tumor suppressor activity." (PMID 22947142, 2012). "Taken together, we have discovered a novel functional connection between PML and the homologous recombination-mediated repair machinery, which might contribute to PML tumor suppressor activity." (PMID 21998700, 2011). "Fluorescent immunostaining of PML bodies was performed in the paraffin-embedded tumor sections." (PMID 19025608, 2008). "Thus, the converging effects of PML upregulation and enhanced assembly of PML-NBs may prompt a heightened oncogenic activity of PML in this tumor type." (PMID 38730056, 2024). "Interestingly, ICP0 itself is targeted for degradation by SIAH-1, demonstrating the complexity of functional consequences of post-translational modification on PML regulation and the close interplay between anti-viral as well as tumor-suppressive defense mechanisms." (PMID 38467608, 2024). "Thus, the conflicting properties of PML may be indicative of specific tumor cell characteristics and the poorly understood functions of individual PML isoforms." (PMID 38069029, 2023). "Thus, PML acts as a tumor suppressor by limiting tumor angiogenesis and EMT." (PMID 37518985, 2023). "Inhibition of these signaling pathways in tumor cells may thus promote PML NBs’ restoration." (PMID 37382966, 2023). "In addition, PIN1 may execute the oncogenic role through promoting the degradation or inactivation of tumor suppressors such as PML and FBXW7." (PMID 36813923, 2023). "PML loss led to an increase in the tumor growth rate in MDA‐MB‐231 cells, but not MCF7 cells." (PMID 37518985, 2023). "Therefore, ATRA/arsenic combination programme exerts an anti‐tumour effect by induced PML/RARA degradation in cells, from which anti‐tumour efficacy could be dissociated from the trancriptomic effect." (PMID 35001521, 2022). "Unravelling further the role of PML in GB progression could set PML as a therapeutic target, aiming at eliminating multiple sub-clones depending on their proliferative and/or invasive phenotype within the heterogeneous GB tumor." (PMID 34208139, 2021). "Since PML bodies have a key role in the control of genomic stability by governing nuclear responses and adaptation to DNA damage or viral stress, enhanced nTRAIL-R2 levels in tumor cells may add to genomic instability, too." (PMID 34333527, 2021).